BMI1 (BMI1 proto-oncogene, polycomb ring finger)
Diseases named in the same sentence as BMI1 in open-access papers (continued):
Sharing a sentence is not in itself a finding about the gene and the disease.
tumor (continued). "In addition, the BMI1 gene plays an important role in cell proliferation and tumor progression." (PMID 19228380, 2009). "First, high BMI1 or EZH2 levels may reflect a different cell of origin for the respective tumours." (PMID 19099573, 2008). "This could indicate a protective role of the BMI-1 protein in this tumour type." (PMID 18475299, 2008). "Since the chromosome 3p kinase (3pK)) is a target of the Ras/Raf/Mek/Erk signaling pathway which antagonizes the function of the oncogene and anti-differentiation factor Bmi-1, 3pK may function as a tumor suppressor in tumors with constitutive Ras/Raf activation." (PMID 16367997, 2005). "According to the authors, therapeutic Bmi-1 inhibition ablates chemoresistant CSCs and rests ACC tumor relapse." (PMID 39866230, 2025). "Key enzymes like EZH2, BMI1, KMT1A, and EHMTs repress tumor-suppressor genes and maintain a proliferative, undifferentiated state." (PMID 40508013, 2025). "The most clinically important genes identified using the random forest method were IRF5 and BMI1; we focused on IRF5, as BMI1 was extensively studied in various tumours." (PMID 39993973, 2025). "FVTF significantly reduced the ability of tumorsphere and soft agar colony formation, the levels of CD44 protein and BMI1, OCT4 and SOX2 mRNAs in HCC cells, and in vivo tumor initiation ability of HCC cells." (PMID 40050970, 2025). "We showed the expression levels of NANOG, BMI1, and SOX2, which are the pluripotency transcription factors involved in the regulation of CSCs, strongly grew along with advanced pathological tumor grade, whereas OCT4 was unchanged." (PMID 40016182, 2025). "Still, Bmi-1 inhibitor PTC209 therapy inhibits the initiation of these cells and the advancement of the tumor." (PMID 39866230, 2025). "BMI1 is significantly overexpressed in NPC and correlates with advanced tumor stage, metastasis, and poor prognosis." (PMID 40623983, 2025). "Collectively, these findings underscore BMI1 as a pivotal therapeutic target in NPC, offering a strategic avenue to disrupt tumor progression, metastasis, and therapy resistance while improving clinical outcomes." (PMID 40623983, 2025). "In vivo, LCa/C@B achieved improved tumor localization, significant Bmi1 knockdown, suppression of CSC populations, and robust inhibition of tumor growth in a primary HCC model." (PMID 41599624, 2025). "This study provides novel insights into the important roles of the miR-200b–BMI-1 and VEGF-A/VEGFR2 axis in regulating ovarian CSCs, tumor neovascularization and chemoresistance." (PMID 41345229, 2025). "CKS1B knockdown significantly reduced the self-renewal capacity and number of CSCs, as evidenced by in vitro tumor sphere formation, increased CD44+CD24+/CD133+ cell populations, and decreased expression of CSCs markers (ABCG2, C-MYC, ALDH1, BMI-1)." (PMID 39897042, 2025). "Regarding tumor proliferation, stable SOX4 overexpression, BMI1 silencing, SOX4 overexpression while silencing BMI1, or control H1299 cells were subcutaneously injected into BALB/c nude mice." (PMID 39349443, 2024). "In the present study, we also found that the tumor-promoting and metastasis-promoting effects of CAF-EVs in vitro and in vivo were compromised by BMI1 knockdown." (PMID 38254031, 2024). "Nuclear SOX2, nuclear or cytoplasmic BMI1, and membranous or cytoplasmic CD24 or CD166 positivity were observed in the tumor cells of AdCC." (PMID 39858584, 2024). "Following chemotherapy, lncRNA DLEU2 and ROR1 were enhanced in BC tumor cells, coupled with the expression of CSCs, EMT-related genes, and BMI1." (PMID 38296962, 2024). "BMI-1 is known as a lymphoid oncogene, whose product acts as a transcriptional repressor of the INK4A-ARF tumor suppressor locus." (PMID 39129784, 2024). "We also performed GSEA using “Bmi-1 targets” as a category, because Bmi-1 is a pivotal gene in CSCs, and we found that it was positively enriched in STEMMED versus the other tumor epithelial clusters." (PMID 38546390, 2024).
tumor (continued). "Tumor sphere formation, ALDH activity, and the expression levels of stemness-related factors (SOX2, BMI1, and CD133) in PCa cells were potently reduced after BHB treatment." (PMID 38555451, 2024). "Nuclear expression of BMI1 and SOX2 and cytoplasmic or membranous staining of CD166 was seen in the tumor parenchyma, while mainly nuclear and occasionally cytoplasmic expression of OCT4 was observed in both parenchymal and stromal cells of MEC in most cases." (PMID 39858584, 2024). "This study confirmed through the mouse orthotopic NSCLC model that compared with Bevacizumab alone, the combination of BMI1 inhibitor PTC-209 and Bevacizumab showed better tumor suppression effect." (PMID 39349443, 2024). "Flow cytometry was used to collect GFP+ CD44+ CCs 14 d after tumor cell transplantation, and qRT-PCR was used to examine the expression of CSC markers (Oct4, Abcg2, Sox2, Bmi1, and Ssea1)." (PMID 38625488, 2024). "Altogether, these findings demonstrate the direct role Bmi-1 plays in EMT and therefore, to the more aggressive stem-like and migratory phenotype of tumor cells." (PMID 36726797, 2023). "In an in vivo mouse model of HNSCC, Bmi-1+ CSCs were enriched in tumors following treatment with Cisplatin and anti-PD-1 therapy, but treatment with the Bmi-1 inhibitor PTC209 prevented induction of these cells and tumor progression." (PMID 36726797, 2023). "Patients with a poor prognosis had tumours with higher levels of the pluripotent markers OCT4 and SOX2, in addition to the polycomb complex protein Bmi-1." (PMID 36968194, 2023). "Here, we found that BMI1, CD44, SOX2, OCT4, UBE2C, CXCR4 CSCs marker genes are significantly upregulated, while IGF1-R, KLF4, ALDH1A1, CD133, FAM3C are downregulated in the tumor core vs healthy mucosa of 24 patients with OSCC." (PMID 38096163, 2023). "And lncRNA CCAT1 directly inhibited microRNA‐218 (miR‐218) and indirectly increased BMI‐1 expression (B lymphoma Mo‐MLV insertion region 1 homolog), then enhanced tumor growth in NSCLC." (PMID 35650713, 2023). "By performing a florescence in-situ hybridization (FISH) experiment of miR-218-1-3p with HCC tumor sections, we showed that in HCC tumors, the expression level of miR-218-1-3p was correlated negatively with BMI1/CTSB expression respectively." (PMID 37923799, 2023). "The TWIST1-JAGGED1-NOTCH-KLF4 axis induces stem cell-like features and metastasis, where KLF4 and BMI1 contribute to TWIST1-induced tumor-initiating capacity, and knockdown of BMI1 expression leads to a reduction in the size and number of tumor spheroids." (PMID 37598158, 2023). "Aberrant expression of PcG proteins like BMI1, CBX8, and EZH2 is mainly responsible for the deposition and maintenance of pro-tumor histone modification in HCC." (PMID 36566204, 2022). "The use of the IL6R monoclonal antibody tocilizumab prevented BMI1 upregulation by blocking IL6 function, demonstrating a reduction in tumor growth in subcutaneous injected xenografts." (PMID 35159370, 2022). "A novel small‐molecule BI‐44 was synthesized, which suppressed BMI1/MCL1 expression and showed significant anti‐tumour effect in preclinical models, providing a new and promising approach for NSCLC treatment." (PMID 35794816, 2022). "The activation of JNK, either by EGFR or chemotherapy agent, stabilizes BMI1 and MCL1 protein expressions through suppressing HUWE1 expression, which then promote tumour initiation and chemo‐resistance." (PMID 35794816, 2022). "The novel small‐molecule BI‐44 developed in this study effectively suppressed BMI1/MCL1 expressions and inhibited tumour initiation and progression in preclinical models." (PMID 35794816, 2022). "Both the tumor spheroid and tumor initiation properties of HNSCC cells can be induced by Twist and Bmi1, and thus Bmi1 is essential for the stem induction ability of TWIST in these cells." (PMID 36076302, 2022).
tumor (continued). "Immunoblot analysis of tumor tissues revealed that Ab27 decreased the phosphorylation of p27Kip1 and STAT3 and the expression of p27Kip1 and BMI1, but had a less substantial effect on the phosphorylation of extracellular signal-regulated kinase 1/2 (ERK1/2)." (PMID 35211652, 2022). "To further elucidate this assumption, we analyzed the protein expression of YAP, BMI1, and SOX4 (stemness-related genes) in tumor tissue." (PMID 35322024, 2022). "The derivatives showing potent anti‐BMI1/MCL1 effect, such as compounds #43–45, were selected for further in vivo anti‐tumour test, in which compound #44 (named as BI‐44 in this study) showed significant anti‐tumour growth effect." (PMID 35794816, 2022). "Selective Bmi-1 inhibitor PTC-209 increases the expression of DKK1 by down-regulating Bmi-1, impairing in vitro osteoclast formation and destroying the tumor microenvironment." (PMID 35897796, 2022). "The results demonstrated that YTHDC1 was significantly and positively correlated with BMI1 and SOX2 mRNA expression levels in HNSCC tumor cells, and that cells with high YTHDC1 expression coexpressed stemness pathway-related genes." (PMID 36411870, 2022). "This is notable due to BMI1-mediated suppression of the INK4A/ARF locus and warrants further investigation into the regulation of this tumor suppressor in T-ALL cells exposed to adipocyte-secreted factors." (PMID 36060800, 2022). "In HCC, overexpression of EZH2 represses miR-622 through H3K27me3 deposition and results in CXCR4 upregulation and unfavorable prognosis, while BMI1 enhances TGFβ2/SMAD pathway and facilitates tumor cell proliferation and cell cycle progression." (PMID 36566204, 2022). "The Bmi-1 protein levels were significantly greater in GAC versus noncancerous tissues, and higher Bmi-1 was significantly correlated with a lower degree of tumor differentiation, higher tumor stages, more lymph node metastasis, and depth of invasion." (PMID 36561502, 2022). "Both fludarabine and ruxolitinib treatments exhibit significant impact on the tumour growth of 22Rv1 line, and diminish the protein level of STAT1, BMI1, SOX2 and NANOG in 22Rv1 tumours when compared with vehicle control." (PMID 35908276, 2022). "BMI1 also preferentially expresses in the side population (SP) of HCC cells and contributes to the maintenance of tumor-initiating ability of SP cells in an immunodeficient mouse mode." (PMID 35455671, 2022). "A novel small‐molecule, BI‐44, was developed, which effectively suppressed BMI1/MCL1 expressions and inhibited tumour formation and progression in preclinical models." (PMID 35794816, 2022). "While only the FOXM1, PYROXD1, hTERT and MCTP1 genes were overexpressed in CRC tumor tissues relative to the normal adjacent tissues at all the stages, but FOXM1, PYROXD1, hTERT, PIM3, BMI1, PPARA and MCTP1 were found to have stage-dependent expression." (PMID 35845311, 2022). "Western blot analysis revealed that the levels of Gli1, BMI1, and SOX2 proteins in the tumor tissues from GANT61-treated mice were significantly lower than that from untreated controls." (PMID 33499351, 2021). "We observed significant changes in tumorigenesis-related markers including CD133, Bmi-1, VEGF, MMP-3, IL-1β, IL-6, TNF-α, and MDR in the tumor group compared with the control group." (PMID 34527741, 2021). "Taken together, these findings indicated that ZEB1, BMI1, and ALDH1A1 were highly expressed in tumor specimens from NSCLC patients with acquired resistance to gefitinib." (PMID 33764690, 2021). "Seven proteins (MYL6, AKAP9, ALDR, HS71A, KHDR1, ROA3, TAGL2) were part of both the BMI1 and RYBP chromatome, four of which (AKAP9, MYL6, ALDR and TAGL2) were identified as upregulated in IDH-wild type GBM samples versus non-tumour using TCGA datasets." (PMID 34316702, 2021). "We found a significant correlation between LSD1 and Bmi-1 in terms of protein intensity and distribution in the HNSCC tumor specimens." (PMID 34689153, 2021).
tumor (continued). "BMI1 and SOX2 have been sought as novel molecular targets for preventing tumor metastasis and recurrence." (PMID 33499351, 2021). "In another study, a murine model of MDA-MB-231 orthotopic tumor was used to evaluate PLGA-block-PEG (PLGA-b-PEG) NPs loaded with docetaxel (DTXL) and small interfering RNA (miRNA) targeting BMI-1." (PMID 34361141, 2021). "We demonstrated that therapeutic blockade of IL-6R inhibits Bmi-1 function and suppresses Cisplatin-induced CSC self-renewal and tumor growth." (PMID 34689150, 2021). "Using immunohistochemistry, we stained a tumor microarray bearing ARMS patient samples and confirmed that BMI1 is expressed at the protein level, with normal pediatric cerebellum shown as a negative control." (PMID 33523558, 2021). "The lineage tracing showed that both PCK+Tomato+ (Bmi1+ CSCs) and PCK+Tomato− tumor cells were eliminated in the regressed SCCs." (PMID 34172737, 2021). "We tested the expression of BMI1 and KLF4 of primary and metastasis tumor in mouse OS xenografts, and the IHC results demonstrated that the expression of BMI1 and KLF4 was higher in metastasis tumor than that in primary (**p < 0.01; ***p < 0.001)." (PMID 33828977, 2021). "Expression of ZEB1, BMI1, and ALDH1A1 was analyzed by immunohistochemistry in tumor specimens from NSCLC patients with acquired resistance to gefitinib." (PMID 33764690, 2021). "Upregulated levels of tumor-suppressive miRNAs, miR-200a, miR-200b, miR-15a, miR-429 and miR-203, lead to downregulation of the PRC1 group of proteins, such as BMI1, RING1A, RING1B and Ub-H2A." (PMID 34360879, 2021). "Mounting evidence supports the notion that aberrant BMI1 and KLF4 expression are responsible for tumor generation, metastasis, and treatment failure." (PMID 33828977, 2021). "B cell-specific Moloney murine leukemia virus integration site 1 (BMI1) is a direct target of miR-15 and via regulating BMI1 through PI3K/Akt pathway, miR-15 inhibited in vivo BLCA cell progression and tumor growth." (PMID 33672684, 2021). "Of note, the described microRNAs target not only EMT‐TFs themselves, but also genes like BMI1, CD44, CD133, JAG1, or MYC that are involved in tumor‐relevant “non‐classical” EMT functions like stemness and survival." (PMID 34459003, 2021). "The NK-exosome-treated tumor group showed a meaningful reduction in the expression of Bmi-1, MMP-3, IL-1β, IL-6, TNF-α, Bax, and Bcl-xL compared with the tumor group." (PMID 34527741, 2021). "B cell-specific Moloney murine leukemia virus integration site 1 (BMI1) is the core component of the PRC1 complex and is reported as an oncogene able to induce cell transformation and self-renewal and promote tumor growth." (PMID 33828977, 2021). "BMI1 and KLF4 were revealed to be direct targets of miR-135a, and miR-135a had a similar effect as the combination of si-BMI1 and si-KLF4 on inhibiting tumor progression and the expression of BMI1 and KLF4 in vivo." (PMID 33828977, 2021). "Although two samples did not match well (samples 4 and 11), the majority of the tumor samples showed a positive correlation for the expression of LSD1 and Bmi-1 at the protein level." (PMID 34689153, 2021). "In vivo, GRP tumor growth was faster and maintained the gene signature: ZEB1‐miR200c‐BMI1 axis; high expression of mesenchymal and stem cell‐related factors; and reduced expression of epithelial marker." (PMID 33764690, 2021). "Several studies have reported that BMI1 is abnormally expressed in HNSCC and correlated with advanced tumor stages, drug resistance, and poor prognosis." (PMID 35048028, 2021). "BMI1 and TWIST1 function together to promote tumor dedifferentiation, metastasis, and development of drug resistance." (PMID 33927214, 2021). "In this study, we found that compared with the tumor group alone, the NK-exosome-treated tumor group exhibited a significant decrease in the expression of CD133, Bmi-1, MMP-3, IL-1β, IL-6, and TNF-α." (PMID 34527741, 2021).
tumor (continued). "The results revealed significant changes including the increased expression of tumorigenesis-related markers, such as CD133, Bmi-1, VEGF, MMP-3, IL-1β, IL-6, TNF-α, and MDR, as well as the apoptotic markers, Bax and Bcl-xL, in the REM134-driven tumor group." (PMID 34527741, 2021). "Several studies show the tumor-suppressive role of miR-200b in PC by targeting different genes, e.g., ZEB1, ZEB2 and Bmi-1." (PMID 33331954, 2021). "We depleted BMI1 using RNAi and inhibitors (PTC‐209 and PTC‐028) and found that this leads to a decrease in cell growth/increase in apoptosis in vitro, and delays tumor growth in vivo." (PMID 33523558, 2021). "The bulk tumor cells were eliminated by the release of DTXL, whereas the released miRNA downregulated the expression of the BMI-1 oncogene in the CSCs, which reduced the expression of the stemness markers and increased the sensitivity of CSCs to DTXL." (PMID 34361141, 2021). "By contrast, miR-15a acts as a tumor suppressor by regulating the expressions of YAP1, DCLK1, BMI1, and Bcl." (PMID 32932969, 2020). "When compared to the tumor of control mice, the tumor of PTC596-treated mice with relapse (mice #5 and #6) had lost many the original characteristics, including reduced BMI1, EZH2, and SOX2 expression." (PMID 31934644, 2020). "FAL1 associates with the epigenetic repressor BMI1 and stabilizes BMI1 protein to modulate the CDKN1A expression and tumor growth." (PMID 31592114, 2019). "Higher expression levels of stem/progenitor cell factors, such as Bmi1, 8-nitroguanine, DNA damage response (DDR) proteins (phosphorylated ATM and γ-H2AX), and manganese-SOD were higher in CD133+ tumor tissues than in CD133- tumor tissues." (PMID 31450710, 2019). "We further determined the expression of Bmi1, MICA/B, GATA2 and p-AMPK in the tumor tissues of different treatment group." (PMID 31088566, 2019). "Results showed that ZBTB28 inhibited NANOG, BMI1, OCT4, KLF4, TIP30 and STAT3 mRNA expression in tumor cells." (PMID 31754389, 2019). "BMI1 is a potential biomarker in EOC management, especially for tumor progression and chemo-resistance." (PMID 29685168, 2018). "Tumor-initiating cells (TICs), also known as cancer stem cells (CSCs), are a small subpopulation of cells in the tumor which can be recognized by several cell surface markers, such as CD133, CD24, CD44, and Bmi-1." (PMID 30081498, 2018). "To do this, we overexpressed the PcG component BMI-1 in HCT116 cells and assessed tumor cell survival in MTT assays." (PMID 28079155, 2017). "For instance, the polycomb family protein BMI-1, designated as a stemness marker for CSC, is important for the self-renewal and tumor initiation of CSCs, and also for neural and hematopoietic stem cells." (PMID 28861107, 2017). "We show that BMI1-mediated repression of the ERK1/2 pathway leads to increased proliferation and tumor burden in primary human MB cells and in a xenograft model, respectively." (PMID 29212025, 2017). "Twist1 in turn activates Bmi1, and both of them are essential for promoting EMT and tumor‐initiating capacity." (PMID 28649800, 2017). "The authors identified CD45- CD90+ CTCs in 91% of samples and demonstrated that this cell population expressed key stem-like genes including Bmi1, CD44, Oct4, Notch1, Wnt3a, Stat3, and HIF-1a compared to CD90+ tumor-tissue cells." (PMID 27738343, 2017). "It has been indicated that Bmi1 acts synergistically with Twist to promote EMT and tumor-initiating capability in OSCC and the increased expression of Bmi1 is correlated with unfavourable prognosis." (PMID 27926533, 2017). "We show increased proliferation of G4 MB cells upon CHD7 silencing in vitro as well as increased tumor volume upon orthotopic xenografting of these cells into NOD/SCID mice, an effect that is dependent on BMI1 expression." (PMID 29212025, 2017).